CD28 (CD28 molecule)
Diseases named in the same sentence as CD28 in open-access papers (continued):
Sharing a sentence is not in itself a finding about the gene and the disease.
tumor (continued). "These pre-exhausted T cells are more prone to be re-invigorated by ICB and indeed, a high signature was found in responder patients mostly with tumor highly infiltrated by CD28+ T cells." (PMID 37898752, 2023). "Of note, the CD28+ cluster was detected also in the tumor, and accordingly it was enriched by ITGA4 (CD49), CCR5 and CD44, all contributing to CD8+ T-cell infiltrative capacity." (PMID 37898752, 2023). "Upon antigen encounter, the ΔIL2RB-z (YXXQ) CAR mediated activation of the JAK-STAT3/5 pathway resulting in superior therapeutic efficacy in multiple tumor models and outperforming conventional CD28 and 4-1BB CAR T cells." (PMID 38090558, 2023). "Its engagement with CD28 and PD-L1 is associated with T cell activation, while it’s binding with CTLA-4 can lead to co-inhibition of T cells leading to tumor immune escape and progression." (PMID 37256148, 2023). "Recently, tumor-specific antigen (TSA) x CD28 bispecific antibody brought hope to direct CD28 stimulation." (PMID 37398660, 2023). "DCs (which are working APCs) endocytose and process the TSAs and then present them to naïve T cells with costimulatory molecules such as CD28 in tumor-draining lymph nodes, leading to the activation of long-term tumor-specific adaptive immunity." (PMID 36039609, 2023). "Pleural T cells, activated and expanded in the presence of CD3/CD28 beads plus IL-2 are potent cytotoxic effectors against autologous tumor as measured by LDH release." (PMID 37063842, 2023). "Our findings indicate that a third-generation CAR-T product combining both CD28 with 4-1BB co-stimulatory domains displays more anti-tumor activity than the second-generation product harboring CD28 alone." (PMID 37626869, 2023). "CTLA-4 ligands, such as B7 molecules, are highly expressed by TAMs and DCs in the tumour microenvironment and their expression directly correlates with the reduction of anti-tumour T cell by inhibiting CD28 in several tumour models." (PMID 36161514, 2023). "Recent studies have shown that magnetic particles modified with T cell activators anti-CD3 and anti-CD28 can effectively induce antigen-specific expansion of T cells in tumor tissue through magnetic guidance and actuation." (PMID 37781535, 2023). "Of course, CD28 should be selected for better anti-tumor activity if the patient has a lower tumor-specific-antigen density and is expected to tolerate cytotoxicity well." (PMID 37298069, 2023). "The contour plot showed that the four effective CD8+ T cell clusters (CD28+, Ifit1+, Ifng+, and Gzmf+ T cells) exhibited significantly higher anti-tumor capacity in Ero1aKO tumors compared with WT counterparts." (PMID 37769655, 2023). "The results indicated that gene expression of cytotoxic T-cells, CD8 and Gzmb, and other T-cells, CD27 and CD28, were higher in the tumor treated with combination of anti-PD-L1 and Fc-VFD than treated with the single treatment." (PMID 35895109, 2023). "In 1996, James Allison and his team discovered that administering antibodies blocking CTLA-4 interaction with CD28 led to increased T-cell activation and tumor rejection." (PMID 37420216, 2023). "For example, CTLA-4 expressed on tumor-infiltrating Treg cells (TI-Tregs) can bind to CD80/86 with higher affinity than CD28, impairing the maturation of APCs and costimulatory signals to further hinder the activation of anti-tumor CD4+ and CD8+ T cells." (PMID 39872303, 2023). "Signatures of heterogeneous tumor infiltrating TRM and “pre-exhausted” long-lived effector-memory CD8+ T cells were associated with better ICB response only in the presence of CD28." (PMID 37898752, 2023). "After donor T cells were activated by CD3/CD28 Dynabeads, we intravenously transferred cells at a 1:1 ratio to tumor-bearing Rag-/- mice, ensuring a confirmed ratio before adoptive transfer." (PMID 38299146, 2023). "This study analyzed the transcription of B4/CD28 members in an OSCC tumor cohort to signify the immune landscape and prognostic value." (PMID 36983005, 2023).
tumor (continued). "PD-L1 expressed on the surface of tumour cells acts as a molecular shield to prevent cytolysis mediated by T cells because PD-1:PD-L1 interaction antagonizes CD28:CD80 co-stimulation." (PMID 37468749, 2023). "Both blocking PD-1 and enhancing CD28 signaling are attractive strategies for driving tumor-targeted T cell activity and persistence in the TME." (PMID 37848682, 2023). "Consistent with the most pronounced expansion of (stem-like) tumor-specific CD8+ T cells in blood, we found the strongest expansion (>10-fold) of CD28+ tumor-specific CD8+ T cells also in blood of triple-treated vs. RT/anti-PD1-treated mice." (PMID 37045833, 2023). "Our results strongly put forward CD28 expression as a key determinant for ICB response in the presence of heterogeneous intra-tumor signatures and different T-cell functional states." (PMID 37898752, 2023). "In contrast, CD137 expression exhibited an increase in PD1+CD28+ T cells with the transition from the periphery to NT and the tumor site." (PMID 37898752, 2023). "In LY2-injected mice, the concentration of detectable IL-17 was considerably lower in IR tumor antigen-stimulated cells compared to cells stimulated with CD3/CD28 antibody." (PMID 37444444, 2023). "CD28 can affect the interaction between PD-1 and PD-L1 and influence T cells’ function in the tumor microenvironment." (PMID 36676763, 2023). "This can lead to an enhanced PD-L1/CD80 cis-heterodimerization that, by preserving the ability of CD80 to activate CD28, can sustain the functionality of intra-tumor CD28+ T cells." (PMID 37898752, 2023). "Although their biological functions (T cell proliferation, cytokine production and tumor cell killing) are similar, CD28 and 4-1BB domains differ in the speed and the level of downstream signaling pathway activation and amplification upon antigen stimulation." (PMID 37779207, 2023). "They detect tumor antigens by detecting MHC class I deficiencies in tumor cells or via the uptake of antigens by dying tumor cells, which activates CD4+ T cells via the T-cell receptor (TCR), CD28, and B-cell responses." (PMID 37894479, 2023). "According to these references, we proposed that LPPC/MP/CD28 suppressed the B16F10 tumor growth by mediating chemokine-cytokine interaction." (PMID 36691089, 2023). "A gradual rise of PD1+CD28+ T cells was found from the periphery to the lung tissue, with a further increase from NT to the tumor site (20% vs 29.5%)." (PMID 37898752, 2023). "On the one hand, the metabolic reprogramming from oxidative phosphorylation towards glycolysis triggered by CD28-mediated PI3K signaling pathway activation is essential for T lymphocytes to exert the tumor-eliminating effector functions." (PMID 37587262, 2023). "It is possible downregulated CD80 and CD86 expression in large A20 tumors is preventing the sustained CD28 signaling required for an effective adaptive anti-tumor response." (PMID 37016127, 2023). "In the MOC2 HNSCC model, IFN-γ production was significantly enhanced in lymph node cells of tumor-bearing mice stimulated with both CD3/CD28 antibodies and IR HNSCC antigens." (PMID 37444444, 2023). "In the present study, we describe a PD1-CD28 CSR that co-opts tumor PD-L1 expression and, at the same time, drives CD28 costimulation." (PMID 37848682, 2023). "Energetic efforts have been placed to improve CAR-T activity in solid tumors by building novel cellular constructs engineered to express immunostimulatory checkpoints including CD28 and OX-40, specific tumor antigens or effector cytokines such as IL-12, IL-18." (PMID 37896948, 2023). "Perhaps the most critical modification to the CAR was the incorporation of the CD28 transmembrane domain to the 4-1BB costimulatory domain, which allowed for durable anti-tumor activity and improved T-cell expansion in recursive tumor cell killing assays." (PMID 37550294, 2023).
tumor (continued). "CD28 costimulatory HER2-specific CARs demonstrated efficient tumor eradication in preclinical animal models, but failed to elicit a therapeutic response in clinical trials." (PMID 37370693, 2023). "The majority of tumor-infiltrating TEMRA cells were CD27+/CD28+ double-positive, which is a characteristic of poorly differentiated effector cells." (PMID 38136380, 2023). "The transduction of CD27 or CD28, for which expression is lost in senescent cells, enhances the survival and anti-tumor effects of CAR-T cells." (PMID 38136380, 2023). "CTLA-4 expressed on T cells blunts the immune system's response to tumor antigens by blocking binding of B7 on antigen-presenting cells (APC) to CD28 on T cells, resulting in suppression of APC function and impaired activation of CD8+ T cells." (PMID 37484200, 2023). "PF displayed significantly higher numbers of CD8+ CD28+ (PD-1-) cells in the stroma compared with the tumor." (PMID 37349318, 2023). "We also noted a pronounced and gradual decline in GrzB production in CD28- T cells, observed from peripheral blood to normal tissue and the tumor site." (PMID 37898752, 2023). "These cells (present in the tumor stroma) usually express immune checkpoints such as PD-1 and CTLA-4, which bind to ligands on the surface of tumor cells (such as PD-L1 and CD28) and suppress the function of immune cells, especially T cells." (PMID 37790928, 2023). "Blocking CD70 with antagonistic antibodies greatly reduces Raji cell stimulation of non-tumor challenged HIS T cells treated with anti-CD3/CD28 in vitro." (PMID 37087494, 2023). "For example, the measured level can be used to determine the threshold of CTLA4 copies and/or the ratio of CD28 to CTLA4 required for the activation of CD8+ cytotoxic T cells for subsequent tumor killings." (PMID 37110545, 2023). "Third-generation CARs have two co-stimulatory domains, most commonly CD28 and 4-1BB, and confer even greater anti-tumor potency on human CAR-transduced T-lymphocytes." (PMID 37420216, 2023). "PD-1 and cytotoxic T-lymphocyte antigen-4 (CTLA-4) receptors inhibit the anti-tumor function of immune cells by blocking CD3/CD28 signaling, which is mediated by the up-regulation of glucose metabolism and interaction with intracellular pathways." (PMID 37158883, 2023). "Further research revealed that modified CD28 s-generation CAR-T cells effectively hindered tumor growth in mice with osteosarcoma or breast tumor xenografts." (PMID 37958672, 2023). "For improved immunotherapy against lung metastasis, researchers designed biomimetic aAPCs (CD-MnOx@CM) using ultrathin MnOx nanoparticles (NPs), which were functionalized with T cell activators (anti-CD3/CD28 mAbs, CD) and tumor cell membranes." (PMID 38075249, 2023). "Polystyrene aAPCs with surface bounding signal 1 (MHC class 1 tetramer) and signal 2 (anti-CD28 and anti-4-1BB) were reported to inhibit subcutaneous tumor growth as well as delay of tumor progression." (PMID 38075249, 2023). "In both CD28− and CD28+ T cells, PD1high frequency increased significantly in NT and further raised at the tumor site." (PMID 37898752, 2023). "CD28 is advocated as a key determinant in the signatures identified, in both periphery and tumor site, thus likely providing feasible biomarkers of ICB response." (PMID 37898752, 2023). "aAPCs showed a longer median survival time (MST) (34 days) compared to the anti-CD28/4-1BB group (28 days) and anti-His group (25 days) in B16 melanoma tumor-bearing mice." (PMID 38075249, 2023). "More established immune markers need to be investigated, such as interferon-gamma, CTLA-4 and CD28, to further characterize the tumor immune microenvironment." (PMID 37175905, 2023). "TRP1high CD8 T cells were treated with DGKi during three distinct time windows: activation with αCD3/CD28, expansion/differentiation, or during coculture with tumor cells." (PMID 38000024, 2023).
tumor (continued). "Combining these results with the findings on clustering trends and diffusion dynamics, we can conclude that large, high-density preformed clusters of HER2.z and HER2.CD28.z CARs were the most beneficial for tumor elimination during the first 25 h." (PMID 37370693, 2023). "Compared to CD28 costimulatory domains, CAR T-cells with 4-1BB costimulatory domains also tend to have lower toxicity due to more mild but persistent tumor killing, compared to the more rapid action of CD28-based CAR-T cells." (PMID 37864230, 2023). "In non-tumor tissues, immune score and the expression of CD28, OX40, CD137, CD27, PD1, TIGIT, and CD39 were significantly higher in patients with recurrence than those without recurrence." (PMID 37313417, 2023). "Tumor treatment with a combination of programmed cell death receptor-1 (PD-1)/programmed cell death ligand-1 (PD-L1) blockage and CD28-based CAR T cells has been intensively studied." (PMID 36835603, 2023). "It was also shown that the majority of infiltrating CTLs in tumor beds exhibited effector (CD8+CD28+), memory (CD45RO+), or activated phenotype (CD25+, CD69+, HLA-DR+) and the naive subset (expressing CD45RA and CCR7) compromised the least proportion." (PMID 37835465, 2023). "Except for LPPC/MP/CD28 complexes, histochemical staining clearly revealed that none of the treatments completely impeded the colonization of tumor cells in the lung." (PMID 36691089, 2023). "CD80 plays an important role in T-cell activation, exerting a dual effect on tumor immunity: it binds to CD28 to provide a costimulatory signal for T-cell activation, and it binds to CTLA-4, resulting in an immunosuppressive effect." (PMID 37765273, 2023). "CD11ahigh was highest in the CD28− T-cell subset in peripheral blood, however a dramatic decline was observed within both subsets with the transition to the tumor site, where the CD28+ T-cell subgroup showed highest expression." (PMID 37898752, 2023). "This was combined with an scFv/CD28 co-stimulatory molecule targeting glypican-3 for increased efficacy towards tumor cells." (PMID 35840635, 2022). "Immune checkpoints such as PDCD1LG2, ICOS, CD28, and CD40 were found to be substantially expressed in the high-risk group, indicating that the tumor microenvironment of the high-risk group had a strong immunosuppressive effect." (PMID 36479092, 2022). "Factors influencing the persistence of CAR T cells include the quality of T cells collected during leukapheresis, CAR design (CD28 < 4-1BB), and the tumor or antigen burden." (PMID 35950202, 2022). "For the trispecific antibody, we see that starting from a low dose, there is a very small portion of unengaged tumor cells, reflecting the ability of tumor to join synapses through both CD28 and CD3." (PMID 35768621, 2022). "CARs are fusion proteins consisting of an antibody-based extracellular target recognition domain and intracellular costimulatory signaling domains (such as CD3, CD28, and 4-1BB) to generate tumor-antigen reactive T-cell clones." (PMID 36248881, 2022). "Tumor cell co-stimulatory or co-repressor signaling, involving genes such as CD28, CD80, CD86 and CTLA4, plays a critical role in regulating cell proliferation, differentiation and cytokine secretion." (PMID 36465397, 2022). "While platelets clearly inhibited cytolytic release of activated CD8+ T cells, except for Granzyme B, tumour cell-induced platelet releasates further enhanced the activation with CD3/CD28/CD2 stimulating antibodies." (PMID 35285006, 2022). "While CD3/CD28 enhanced T cell proliferation, MDSCs isolated from the spleen of tumor-bearing mice implanted with parental 545 or sgATP11b-545 cells partially or completely inhibited T cell proliferation." (PMID 35025764, 2022). "Bispecific antibodies are designed to recognize and bind specific tumor-associated antigens (e.g. AFP, GPC3) and effector cell receptors (e.g. CD3, CD28) in order to initiate tumor cytotoxicity." (PMID 35433430, 2022).
tumor (continued). "These T cell antigen coupler (TAC)-receptors outperformed CD28-based CARs in a solid tumor model, exerting a more efficient tumor rejection, reduced toxicity, and increased tumor infiltration." (PMID 36077730, 2022). "As a result, superior in vivo anti-tumor activity was consistently achieved by pCAR T-cells compared to linear CAR T-cells in which either CD28 or 4-1BB (2G CAR) or both of these domains (third generation CAR) had been included." (PMID 35222427, 2022). "When ALPN-202 was combined with anti-CD28, anti-tumor activity was significantly reduced compared to ALPN-202 administration alone." (PMID 35379805, 2022). "Then, we analyzed the correlation between SLC3A2 expression and 60 immune check-point genes, of which 24 were stimulatory, like ICOS and CD28, while the other 36 genes were inhibitory for anti-tumor immunity, such as PD1 and PDL1 (CD274)." (PMID 35992269, 2022). "Splenic CD8+ T cells from naive mice were stimulated with anti-CD3 and CD28 antibodies and co-cultured with MDSCs isolated from tumour-bearing vehicle- or PI-3065-treated mice." (PMID 35986086, 2022). "After T cell accumulation in the tumor mediated by bispecific naiv̈e T cells and tumor cells aptamers, T cells in the tumor site were subsequently activated in situ via CD3/CD28 T cell activator to induce tumor killing." (PMID 34987632, 2022). "This approach can be extended in other formats beyond CD28 such as by engaging two antigen targets on tumor cells to promote tumor-directed specificity." (PMID 35768621, 2022). "And the expression of HAVCR2, CCR7 and CD28 had poor correlation with the clinicopathological features of PCa in age, GS and tumor stage." (PMID 36505767, 2022). "Once the scFv portion recognizes and binds a tumor antigen, the intracellular 4-1BB or CD28 co-stimulatory domain and CD3ζ signal to the intracellular downstream pathway." (PMID 36389701, 2022). "TILs isolated from tumor tissue were activated using CD3/CD28 and stained for T cell markers and IFN-γ." (PMID 36430552, 2022). "CD28 was also upregulated in the tumor from the apoE-/- mice in which wt tumor cells were inoculated (wt/apoE-/-)." (PMID 36341364, 2022). "The PD-1/CD28 CSR reverses inhibitory signals transmitted by tumor cells, whereas the IL-4/7 ICR reverses inhibitory effects of IL-4." (PMID 35392217, 2022). "Cell surface co-expressions of PD-1/CD28 in tumor infiltrating CD8+ T cells are positive signs for successful ICT2,47." (PMID 35013322, 2022). "For instance, by combining CD28 and OX40 co-stimulatory domains, an earlier effector phenotype is merged with persistence and a long-lasting anti-tumor response, superior to that of CD28/4-1BB-incorporated CAR-T cells." (PMID 35053463, 2022). "In the case of BBζ CAR-T cells, initial responses are more gradual relative to CD28, and often illustrate residual tumor burden which can provide lingering stimulation to the CAR-T cell population." (PMID 36139142, 2022). "Strikingly, supernatant containing T cells activated by general anti-CD3/CD28 stimulation also resulted in kill of 5T4− tumor cells." (PMID 36271507, 2022). "Preclinical experiments revealed that cMet-PD1/CD28-CAR-T cells had higher anti-tumor effects and safety than traditional c-Met CAR-T cells." (PMID 35392217, 2022). "Cluster 3 was present in the circulating and tumor compartments and was composed of heterogeneous PD-1- and PD-1dim cells with high levels of CD28, CD127, and TCF-1." (PMID 35584630, 2022). "HPBMC were activated and expanded with anti-CD3/CD28 antibodies and IL-2, before co-culturing with tumor cells." (PMID 35154166, 2022). "Primary T cells equipped with the CD28 or 4-1BB-based CARs were demonstrated with potent anti-tumor efficacy both in vitro and in vivo." (PMID 35252208, 2022). "What is also important, is that there are reports showing that 4-1BB-CAR-T cells exhibit superior proliferation, in vivo persistence and tumor elimination compared to CD28-CAR-T cells." (PMID 36428480, 2022).